C3AR1 (complement C3a receptor 1)
Diseases named in the same sentence as C3AR1 in open-access papers (continued):
Sharing a sentence is not in itself a finding about the gene and the disease.
prion disease (5 papers, 2018 to 2022). A transmissible disease that is caused by a protein that is able to induce abnormal folding of normal cellular proteins, leading to characteristic spongiform brain changes, which are associated with neuronal loss without an inflammatory response. "To investigate the role of some of these proteins in prion disease of the CNS, we infected mice deficient in DAMP receptor genes Tlr2, C3ar1, and C5ar1 with 22L scrapie." (PMID 30596651, 2018). "Though complement components C3 and C5 are not required for prion pathogenesis, the G protein-coupled receptors C3aR1 and C5aR1 might influence prion disease by interacting with other unidentified ligands to elicit a response." (PMID 30596651, 2018). "Interestingly, depletion of any of the DAMP receptor genes Tlr2, C3ar1, and C5ar1 in a prion mouse model only led to a slightly increased survival in the Tlr2-model, while C3ar1, and C5ar1 did not influence prion disease course." (PMID 36230910, 2022).
renal carcinoma (5 papers, 2020 to 2023). A carcinoma arising from the epithelium of the renal parenchyma or the renal pelvis. "C3ar1 expression has been linked to renal tumors and normal tissues in some studies, while C3ar1 expression is elevated in renal carcinomas." (PMID 38045624, 2023). "Using the co-expression tool on expression data extracted from renal cancer cell samples of CCLE, we obtained lists of genes that were co-expressed with FN1, C3, and C3AR1 and harbored a correlation coefficient > 0.5 or < − 0.5 and P-value < 0.01." (PMID 34688260, 2021).
retinal degeneration (5 papers, 2014 to 2025). Degeneration of the retina. "In this study, we show that the expression of C3 and C3a receptor (C3ar1) is positively associated with the inflammatory response and retinal degeneration." (PMID 36110094, 2022). "We conclude that deletion of the anaphylatoxin receptor C3aR1 cannot modulate mononuclear phagocytes but diminishes retinal degeneration through interference with the complement pathway and thus decreased MAC assembling." (PMID 39775695, 2025). "Although C3ar1 is involved in retinal development and neuropathy, the role of the C3-C3ar1 axis in retinal degeneration is less understood." (PMID 36110094, 2022). "To better determine the role of C3ar1 in retinal degeneration, we searched the STRING database and constructed the protein interaction network centered on C3ar1." (PMID 36110094, 2022). "Together, these bioinformatics data suggest that the activation of the C3a-C3ar1 signaling pathway contribute to retinal degeneration through regulation of the inflammatory response and immune cell activation." (PMID 36110094, 2022). "Additionally, given the complexity and the degree of crosstalk between various immune pathways, other transcription factors (TFs), such as Hmox1, NFkB, and NFE2L2, might also interact with the C3a-C3ar1 pathway and be involved in retinal degeneration." (PMID 36110094, 2022).
diabetes (4 papers, 2019 to 2025). "Reports have shown that C3AR1 is a key regulatory gene in metabolic diseases such as type 2 diabetes mellitus and fatty liver." (PMID 40939011, 2025).
gastric cancer (4 papers, 2017 to 2025). A primary or metastatic malignant neoplasm involving the stomach. "Overlap analysis with genes that co-expressing in 381 gastric cancer tissues and 37 gastric cells demonstrates that various immune related genes such as CCL18, TLR8, C3AR1, CYSLTR2 and CD86 are positively correlated with CD163." (PMID 29152078, 2017). "Furthermore, results from Protein Atlas database validate immune molecules including CD86, CD209, C3AR1, CLEC4D, CLEC7A and CYSLTR2 are positive in gastric cancer cells." (PMID 29152078, 2017).
lupus (4 papers, 2019 to 2025). "To identify the upstream and downstream relationships of these upregulated genes (C1q, C3, C3aR1, C5aR1, CR3, and CR4), we performed KEGG pathway analysis using the lupus mouse microarray database." (PMID 34433493, 2021).
endometriosis (3 papers, 2019 to 2023). The growth of functional endometrial tissue in anatomic sites outside the uterine body. "The increased expression of ITGB2 had been previously reported in endometriosis tissues compared with normal tissues, and high C3AR1 expression might be used as a diagnostic factor for the endometriosis-associated malignant phenotype." (PMID 36660246, 2023). "Compared with the control group, high C3, VCAM1, ITGB2, and C3AR1 expression had statistical significance in endometriosis among the hub DEIRGs." (PMID 36660246, 2023). "From network analysis, we identified a novel linker gene, C3AR1, which had not been implicated previously in endometriosis." (PMID 31879572, 2019). "Interestingly, one of those linker genes (C3AR1) is within the 165 full gene list, which was identified by overlapping analysis between literature-based endometriosis-related genes and one set of GEO datasets." (PMID 31879572, 2019). "Finally, we explored a novel linker gene, C3AR1, which had not been implicated previously in endometriosis." (PMID 31879572, 2019). "Other members of the complement activation pathway, such as complement C3a receptor 1 (C3AR1) and V-set and immunoglobulin domain containing 4 (VSIG4), are also known in endometriosis, and upregulation of complement and coagulation pathways in endometriosis has been well-reported in several studies." (PMID 36339397, 2022).
glaucoma (3 papers, 2019 to 2024). Increased pressure in the eyeball due to obstruction of the outflow of aqueous humor. "It is possible that C3AR1 signaling does not strongly affect phagocytosis or synapse loss in an ocular hypertensive setting and that C3AR1 signaling has detrimental effects in glaucoma through a different mechanism." (PMID 33176797, 2020). "To test the function of complement activation peptide C3a in a chronic, age-related model of glaucoma, we backcrossed a null allele of the C3a receptor (C3ar1-) into DBA/2J mice." (PMID 33176797, 2020). "In the current datasets, optic nerve head monocyte-like cells highly express various complement genes (including C1qa, C1qb, C1qc, C3, and C3ar1), and complement activation is implicated in human glaucoma." (PMID 30670050, 2019). "Signaling through C3AR1 promoted neurodegenerative processes in a model of glaucoma with chronic ocular hypertension and neuroinflammation." (PMID 33176797, 2020). "More work is required to elucidate the full role of complement pathway molecules in specific cell types during glaucoma and the current data open an avenue for functionally exploring additional key molecules such as C3ar1." (PMID 30670050, 2019). "Therefore, C3AR1 is emerging as an important player in glaucoma, and its role in the activation of microglia and neuroinflammation in the retina offers a new potential therapeutic target." (PMID 38396986, 2024). "A larger study using DBA/2J mice or another model with chronic ocular hypertension could address how C3ar1 alters microglia and monocyte localization and function in this type of glaucoma." (PMID 33176797, 2020). "In addition, a significant increase in C3ar1, the receptor for the anaphylatoxin C3a, was also detected in the ONH of DBA/2J mice in the early stages of glaucoma, with expression localized to microglia and infiltrating myeloid cells." (PMID 38396986, 2024).
multiple myeloma (3 papers, 2016 to 2024). "In conclusion, a total of 393 DEGs were identified between osteocytes co-cultured with and without myeloma cells, and KLF4, IRF8, EGF, EGR1, S1PR1, C3AR1, and NPY1R might be involved in osteocyte cell apoptosis induced by MM cells." (PMID 27405725, 2016).
renal cell carcinoma (3 papers, 2020 to 2022). "C3AR1 is crucial for the protective factor and an independent risk factor for renal cell carcinoma." (PMID 35630098, 2022).
uveitis (3 papers, 2017 to 2025). An inflammatory process affecting a part of or the entire uvea. "In a mouse model of experimental autoimmune uveitis (EAU) less severe uveitis in C3aR1/C5aR1-double KO mice than control mice was evident, involving reduced T cell response." (PMID 39775695, 2025).
acute myeloid leukemia (2 papers, 2021 to 2023). Acute myeloid leukemia (AML) is a group of neoplasms arising from precursor cells committed to the myeloid cell-line differentiation. "As previous studies, C3AR1 mRNA overexpression in the early stages of acute myeloid leukemia could predict shorter survival time." (PMID 33748161, 2021).
amyloid (2 papers, 2020 to 2025). "In vivo, germline or conditional ablation of C3aR1 in APP/PS1 or 5xFAD amyloidosis mouse models has not been reported." (PMID 31924226, 2020). "Herein, we show that TLQP-21 activation of C3aR1 increases microglial migration and phagocytosis, and that icv TLQP-21 administration to male 5-month-old 5xFAD mice reduces amyloid plaque burden and microgliosis, and restores expression of a subset of AD-associated genes to wild type levels." (PMID 31924226, 2020).
endotoxemia (2 papers, 2020 to 2024). "Thus, endotoxemia leads to positive correlation between expression of IL-1β and complement receptor gene C3AR1 in humans." (PMID 38236896, 2024).
fibrosis (2 papers, 2021 to 2025). the formation of excess fibrous connective tissue in an organ or tissue in a reparative or reactive process. "C3aR1 deletion in Kupffer cells does not affect weight gain, glucose homeostasis, liver steatosis or fibrosis." (PMID 39773465, 2025). "C3aR1 deletion in all macrophages does not affect weight gain, glucose homeostasis, liver steatosis or fibrosis." (PMID 39773465, 2025).
Hepatic steatosis (2 papers, 2025). Steatosis is a term used to denote lipid accumulation within hepatocytes. "Deletion of C3aR1 in the macrophage population throughout the body, or specifically in Kupffer cells, did not affect weight gain, glucose homeostasis, or extent of hepatic steatosis/fibrosis." (PMID 39773465, 2025). "Deletion of C3aR1 in macrophages generally, or in liver resident macrophages specifically, had no major effect on systemic glucose homeostasis and hepatic steatosis, inflammation, and fibrosis in this murine dietary model of MASLD/MASH." (PMID 39773465, 2025).
Hyperglycemia (2 papers, 2023 to 2025). An increased concentration of glucose in the blood. "According to our data, hyperglycemia alone caused upregulation of a number of genes such as TGFA, CDCA5, MUC3A and C3AR1." (PMID 37511575, 2023).
multiple sclerosis (2 papers, 2023 to 2025). A progressive autoimmune disorder affecting the central nervous system resulting in demyelination. "C3aR1 and C5aR1 might be involved in local tissue repair similar to their upregulation in multiple sclerosis for demyelination and remyelination." (PMID 37207197, 2023).
ocular hypertension (2 papers, 2020 to 2025). Abnormally high intraocular pressure. "Development of iris disease, ocular hypertension, optic nerve degeneration, retinal ganglion cell activity, loss of RGCs, and myeloid cell infiltration in C3ar1-deficient and sufficient DBA/2J mice were compared across multiple ages." (PMID 33176797, 2020). "In line with our data, C3aR1 was identified as a damaging neuroinflammatory factor in ocular hypertensive DBA/2J mice, influencing the microglial expression pattern and being associated with the risk of degeneration." (PMID 39775695, 2025). "Immune cells that are likely to express C3ar1 contribute to iris damage and the development of ocular hypertension." (PMID 33176797, 2020). "Deficiency in C3ar1 lowered the risk of degeneration in ocular hypertensive mice without affecting intraocular pressure elevation at 10.5 months of age." (PMID 33176797, 2020). "Thus, C3ar1 deficiency did not have a general effect on the number of these cells in neural tissue exposed to ocular hypertension." (PMID 33176797, 2020). "Thus, C3ar1 deficiency did not prevent changes in RGC activity associated with ocular hypertension." (PMID 33176797, 2020). "However, it has not been determined whether C3AR1 has an effect on IL10 production or the expression of related genes and proteins in microglia in an ocular hypertensive setting." (PMID 33176797, 2020).
periodontitis (2 papers, 2025). An acute or chronic inflammatory process that affects the tissues that surround and support the teeth. "Compared to C3ar1+/+ and C3ar1+/− mice, C3ar1−/− mice showed significantly less ligature-induced bone loss, suggesting that C3aR receptor deletion mitigates alveolar bone loss in periodontitis mice." (PMID 40240339, 2025). "Notably, CD81+ fibroblasts exhibited the highest expression of the C3 ligand compared to other fibroblast subgroups, while the C3 receptor (C3aR1) was exclusively expressed by neutrophils in periodontitis." (PMID 40801798, 2025). "Notably, after the onset of periodontitis, the expression of the C3 gene in periodontal fibroblasts and the C3ar1 gene in macrophages both significantly increased." (PMID 40240339, 2025). "Furthermore, C3ar1−/− periodontitis mice showed reduced collagen fiber degradation compared to C3ar1+/+ and C3ar1+/− genotype periodontitis mice." (PMID 40240339, 2025). "In human periodontitis gingiva, we found that CD81+ fibroblasts might activate neutrophils via the C3/C3aR1 axis to exaggerate inflammation." (PMID 40801798, 2025).
schizophrenia (2 papers, 2021 to 2025). A major psychotic disorder characterized by abnormalities in the perception or expression of reality. "Resolving when and where C3ar1 is needed are questions of significant translational importance because, as a G-protein-coupled receptor, human C3AR1 serves as a potential therapeutic target for disorders associated with complement upregulation, such as schizophrenia." (PMID 41306817, 2025).
staphylococcus aureus infection (2 papers, 2016 to 2021). An infectious process in which the bacteria Staphylococcus aureus is present. "The second-ranked pathway (though non-significant) was Staphylococcus aureus infection, represented by DEFA4, C3AR1, and HLA-DMB." (PMID 34442377, 2021).
stomach adenocarcinoma (2 papers, 2023). "Increased C3AR1 suggests poor prognosis in patients with gastric adenocarcinoma, and leads to an increase in suppressive tumor immune cell." (PMID 37005667, 2023). "Current researches on C3AR1 in tumors mainly focuses on stomach adenocarcinomas (STAD), and kidney renal clear cell carcinoma (KIRC)." (PMID 37005667, 2023). "In stomach adenocarcinoma (STAD), a high expression of C3AR1 is positively correlated with increased tumor immune infiltration, as well as poor prognosis." (PMID 37370848, 2023).
acute coronary syndrome (1 paper, 2011). Signs and symptoms related to acute ischemia of the myocardium secondary to coronary artery disease. "In addition, signaling via C3aR1 promotes plaque instability and can thus result in clinical sequelae of acute coronary syndromes." (PMID 21827714, 2011).
aneurysm (1 paper, 2022). Bulging or ballooning in an area of an artery secondary to arterial wall weakening. "Human aortic samples were collected from MFS and non-MFS aneurysm patients to study complement factor gene expression C1R, C1S, C3AR1, and C5AR1 and SMC gene ACTA2." (PMID 36279189, 2022).
Apathy (1 paper, 2025). Apathy is a quantitative reduction of interest, motivation and the initiation and persistence of goal-directed behavior, where often the accompanying emotions, thoughts, and social interactions are also diminished. "C3 (r = 0.6907) and its receptor C3ar1 (r = 0.8596), key components of the C3 signaling pathway, were positively correlated with apathy." (PMID 41377997, 2025). "Composite apathy scores were strongly and positively correlated with mRNA fold changes for all examined genes: Tyrobp, Trem2, C1qa, C1qb, C1qc, C3, C3ar1, and Cd33 (p < 0.0001)." (PMID 41377997, 2025).
carotid atherosclerosis (1 paper, 2024). A thickening and loss of elasticity of the walls of carotid arteries that occur with formation of atherosclerotic plaques. "This gene is not only a key gene in carotid atherosclerosis, but also its signaling pathway C3a/C3aR1/VCAM1 mediates neuroinflammation in aging and neurodegenerative diseases." (PMID 38694921, 2024).
Cirrhosis (1 paper, 2025). A chronic disorder of the liver in which liver tissue becomes scarred and is partially replaced by regenerative nodules and fibrotic tissue resulting in loss of liver function. "Further work is needed to elucidate the mechanisms of the role of C3aR1 in the pathogenesis of MASH and cirrhosis." (PMID 39773465, 2025).
coronary atherosclerosis (1 paper, 2011). Atherosclerosis of the coronary vasculature. "At protein level, advanced human coronary atherosclerosis plaques express C3aR1 in contrast to normal coronary intima." (PMID 21827714, 2011).
diffuse large B-cell lymphoma (1 paper, 2023). "However, C3AR1 mRNA expression levels in adrenocortical carcinoma (ACC), lymphoid neoplasm diffuse large B-cell lymphoma (DLBC), lung squamous cell carcinoma (LUSC), and thymoma (THYM) are lower than normal tissues." (PMID 37005667, 2023).
esophageal squamous cell carcinoma (1 paper, 2023). Esophageal squamous cell carcinoma (ESCC) is a type of esophageal carcinoma (EC) that can affect any part of the esophagus, but is usually located in the upper or middle third. "By affecting the polarization of M2 macrophages, C3AR1 may lead to an immunosuppressive microenvironment, as a result, leading to the progression of esophageal squamous cell carcinoma." (PMID 37370848, 2023).
hyperreactivity (1 paper, 2023). "C3ar1 is active during complement activation, and C3ar1 mutant mice were shown to be protected from antigenic attack‐induced airway hyperreactivity." (PMID 38045624, 2023).
insulinoma (1 paper, 2021). "Studies in insulinoma and CHO cells, revealed different potencies of the two peptides, and moreover, stimulation of insulin secretion by TLQP-62 in insulinoma cells was not blocked by the C3aR1 antagonist SB290157." (PMID 34626205, 2021).
invasive ductal breast carcinoma (1 paper, 2021). The most common type of invasive breast carcinoma, accounting for approximately 70% of breast carcinomas. "Oncomine database analysis showed that C3AR1 was highly expressed in both primary and invasive ductal breast carcinoma." (PMID 35047378, 2021).
liver disease (1 paper, 2025). "To test the role of complement 3a receptor (C3aR1) on macrophages and liver resident macrophages in MASLD, we generated mice deficient in C3aR1 on all macrophages (C3aR1-MφKO) or specifically in liver Kupffer cells (C3aR1-KpKO) and subjected them to a model of metabolic steatotic liver disease." (PMID 39773465, 2025).
lymph node metastasis (1 paper, 2023). "Morever, it was found that C3AR1 expression was related to tumor grade, stage, recurrence, lymph node metastasis and survival status." (PMID 37005667, 2023).
muscular dystrophies (1 paper, 2022). "The relationship between C3aR1 and C5aR1 and vessel remains obscure and is not yet reported in muscular dystrophies." (PMID 36402750, 2022).
neuropathy (1 paper, 2022). A disorder affecting the nervous system that manifests with pain, tingling, numbness, and/or muscle weakness. "A previous study indicated that C3ar1 regulates the expression of STAT3 and mediates inflammation during neuropathy, which is not clear in the retina." (PMID 36110094, 2022).
Parkinson disease (1 paper, 2023). A progressive degenerative disorder of the central nervous system characterized by loss of dopamine producing neurons in the substantia nigra and the presence of Lewy bodies in the substantia nigra and locus coeruleus. "Moreover, the high expression of C3AR1 was found to be highly enriched in Parkinson’s disease, while the low expression of C3AR1 was associated with the notch signaling pathway." (PMID 37492566, 2023).